LEP (leptin)
Diseases named in the same sentence as LEP in open-access papers (continued):
Sharing a sentence is not in itself a finding about the gene and the disease.
Obesity (continued). "Several factors may explain this: men with obesity frequently have elevated serum levels of insulin, IGF-1, and leptin, with reduced adiponectin levels—all of which have been associated with prostate cancer in some studies." (PMID 40002302, 2025). "Leptin, FAS, CEBP/α, and SREBP/1c are adipogenesis‐related genes, and obesity may induce abnormal expression of these genes." (PMID 39968210, 2025). "In islets isolated from leptin-resistant ZDF fa/fa rats, palmitate oxidation is decreased by 77% compared to nondiabetic lean control fa/+ rats, consistent the lipid accrual in this model of obesity and T2D." (PMID 39814231, 2025). "Additionally, AT-II significantly reduced the elevated serum leptin levels induced by HFD feeding, further confirming its anti-obesity effects in DIO mice." (PMID 41492457, 2025). "Phloretin treatment can regulate serum levels of leptin, adiponectin, triglycerides, LDL, and free fatty acids in obese mice, aligning with our findings and suggesting its potential in treating obesity and metabolic disorders." (PMID 41354995, 2025). "Cafeteria diet induced significant obesity (mean weight 426.76 g vs. 263.09 g controls, p < 0.001) and increased leptin levels without altering insulin, IGF-1, or inflammatory markers." (PMID 40806434, 2025). "In obesity and GDM, elevated leptin levels lead to leptin resistance, reducing its effectiveness." (PMID 41302116, 2025). "The serum adiponectin/leptin ratio exhibited significant negative correlations with both subcutaneous and visceral adipocyte geometries in participants without obesity and with visceral adipocyte geometries in participants with obesity." (PMID 41271970, 2025). "Activation of CB1 receptors has been shown to lead to changes in eating habits that are partially dependent on leptin levels, while increased stimulation of CB1 receptors may lead to obesity." (PMID 40283681, 2025). "Obesity leads to leptin resistance in relation to the anorexigenic effect but not in relation to the sympathetic nervous system." (PMID 39949590, 2025). "Interestingly, semaphorins are also important players in monogenic obesity being involved in neuronal projection of pro-opiomelanocortin (POMC) neurons and thereby, contributing to neuronal circuitry in the leptin-melanocortin pathway." (PMID 41225618, 2025). "The development of leptin resistance may lead to elevated glutamate and GABA levels which promote feeding, and this in turn may exaggerate the obesity condition." (PMID 41309900, 2025). "In obese mice, increased LEP and inflammatory cytokines reflect an excess energy status; however, paradoxically, obesity may suppress kisspeptin expression and impair HPG axis function due to LEP resistance and inflammatory interference." (PMID 40689179, 2025). "Because we selectively targeted Arc non-LepR neurons in our obesity model, we reasoned that the function of LepR neurons should remain intact and, therefore, leptin action should be maintained." (PMID 40540394, 2025). "Not surprisingly, leptin, an important metabolic hormone, was found to be increased in the circulation of the psoriatic–obesity group, especially in the group that was continuously subjected to the W diet." (PMID 40869018, 2025). "One concern is that Set is used for weight loss only in patients with mutations in the POMC/leptin/MC4R pathways, but not in the most common polygenic form of obesity." (PMID 40232848, 2025). "Another study of oxytocin treatment in leptin-resistant db/db mice resulted in an amelioration of obesity via vagal afferent neurons not requiring leptin actions." (PMID 41016636, 2025). "Biomarkers like leptin, adiponectin, and CRP can identify nonresponders to treatments, high‐risk patients, and specific obesity‐related complications, guiding individualized therapeutic strategies." (PMID 40551726, 2025).
Obesity (continued). "Obesity contributes to tumor progression not only through excess adiposity but also via a chronic inflammatory state characterized by elevated cytokines (e.g., IL-6, TNF-α) and adipokines such as leptin." (PMID 41008885, 2025). "In a murine model, animals with induced obesity PDAC grew larger, and serum leptin was higher." (PMID 40940878, 2025). "Notably, rare, pathogenic mutations in all the genes involved in leptin driven melanocortin pathway (LEP, LEPR, POMC, PCSK1, MC4R, primarily) lead to severe early-onset obesity accompanied by eating disorders." (PMID 39237720, 2025). "As studies have shown minimal impact of leptin replacement therapy on common obesity, leptin analogues have currently no role in treatment of common obesity." (PMID 39929239, 2025). "After multivariate adjustment, women with obesity showed a 63% higher probability of presenting altered leptin levels compared with those without obesity." (PMID 41439942, 2025). "There was a positive correlation of leptin with obesity markers (BMI and WC) and a negative correlation with glycemic parameters (FPG, 2hPG, and HbA1c) as well as insulin resistance (HOMA-IR)." (PMID 40630340, 2025). "This is notably exacerbated in individuals with obesity, where excess adipose tissue acts as a potent source of pro-inflammatory cytokines such as IL-6, TNF-α, and leptin, which have been shown to enhance tumor cell proliferation, migration, and immune evasion." (PMID 41139205, 2025). "However, utilizing a genetic model may influence the translatability of our findings, since human polygenic obesity is not characterized by leptin deficiency, and leptin itself might overlap with the modulation of metabolic pathways affected by SGLT2i treatment." (PMID 40059147, 2025). "Furthermore, IH and sleep fragmentation also induce metabolic dysregulation, impairing insulin sensitivity, promoting adipose inflammation, and increasing leptin resistance which contribute to the bidirectional link between OSA and obesity/metabolic syndrome." (PMID 41517455, 2025). "Other studies have shown that Bbs2-, Bbs4-, and Bbs6-knockout mice are leptin resistant, independent of obesity; and in these models, hypothalamic leptin receptor signaling was impaired." (PMID 40519161, 2025). "Obesity may impact the HPO axis through multiple mechanisms, including by inducing a state of leptin excess, promoting insulin resistance, and favoring a pro-inflammatory environment." (PMID 40755647, 2025). "The concentration of leptin present in the bloodstream in a non-fasting state is significantly correlated with the development of obesity because of its expression in adipose tissue." (PMID 40142488, 2025). "HFD led to greater body weight, serum cholesterol, glucose, and elevated levels of pro-inflammatory cytokines and adipokines, such as leptin, resistin, PCSK9, and DPPIV/CD26, consistent with findings that obesity drives chronic inflammation and metabolic dysregulation." (PMID 40998975, 2025). "However, this contradicts previous studies, which demonstrate a higher prevalence of obesity in SOD, justified by hypothalamic defects that can lead to metabolic changes (hyperphagia, insensitivity to leptin) and favor weight gain." (PMID 39395814, 2025). "Furthermore, in obesity, VEGF level depression was 53 percent, and leptin concentration was reduced by 54 percent compared with the normal placental tissue value." (PMID 41302116, 2025). "Leptin is involved in the upregulation of IL-6 and TNF-α, contributing to obesity-related low-grade inflammation, promoting vascular dysfunction by contributing to hypertension, angiogenesis, and atherosclerosis, and interacting with insulin, affecting glucose and lipid metabolism." (PMID 40724644, 2025). "In mice with obesity-induced leptin resistance, chronic Oxt treatment improved the short-term satiety effects of leptin, but this outcome eventually reversed, and oxytocin did not maintain sensitivity for a chronic period." (PMID 41016636, 2025).
Obesity (continued). "We determined the circulating concentrations of adiponectin, leptin, resistin, TNFα, and IL-6 in participants with obesity and type 2 diabetes with and without obesity, and compared them to those of the control group." (PMID 40095937, 2025). "This phenomenon, often referred to as “leptin resistance,” plays a significant role in the pathophysiology of obesity, where despite high levels of leptin, the CNS fails to adequately respond, leading to continued overeating and reduced energy expenditure." (PMID 40500780, 2025). "Unlike hs-CRP, leptin provides more specific insights into obesity driven metabolic dysfunction, making it a valuable predictor of insulin resistance and cardiovascular risk in PCOS patients." (PMID 40385768, 2025). "The observed LEP upregulation in the OBS treatment group aligns with evidence suggesting that folic acid influences lipid metabolism, insulin sensitivity, and inflammatory pathways in obesity models." (PMID 40292473, 2025). "The positive association of leptin with disordered-eating indices is compatible with leptin resistance in obesity, where elevated leptin fails to suppress appetite and reward-driven intake." (PMID 41356005, 2025). "Multiple regression analysis identified the serum adiponectin/leptin ratio as an independent predictor of adipocyte geometries in both participants with and without obesity, and body weight in individuals without obesity." (PMID 41271970, 2025). "Disruptions in the methylation of adipokine-related genes such as LEP and ADIPOQ may elevate risks for obesity, cardiovascular disease, and metabolic syndrome." (PMID 41374021, 2025). "Among the obesity, upregulation of transforming growth factor-β1 (TGF-β1) in the kidney is induced by elevated leptin levels, promoting extracellular matrix accumulation, which leads to glomerular and tubular basement membrane thickening, glomerulosclerosis, and tubulointerstitial fibrosis." (PMID 40786694, 2025). "However, elevated leptin levels in obesity increased SOCS3 expression, which in turn inhibits JAK2–STAT3 activation and further reduces leptin signaling and sensitivity." (PMID 41516046, 2025). "(2017) showed that, compared to normal-weight adolescents with PCOS, a group of adolescents with obesity and PCOS had significantly lower levels of SHBG and HDL-C and significantly higher levels of triglycerides, leptin, fasting insulin, LDL-C and free testosterone." (PMID 40491594, 2025). "Unlike causal genes for monogenic obesity, such as MC4R or LEP, which have a direct role in early-onset and severe forms of obesity, FTO influences susceptibility through regulatory mechanisms." (PMID 40806129, 2025). "Previous studies found that elevated levels of leptin, hs-CRP, IL-6, and reduced levels of adiponectin are linked to obesity, but not necessarily diabetes." (PMID 39940942, 2025). "Since leptin is elevated in the stomach of mice in response to a HFD and in patients with obesity, it appears to be possible that enhanced gastric leptin might contribute to gastric FGF23 production." (PMID 40483378, 2025). "Leptin has been anticipated as a potential obesity treatment, but its clinical application has not become widespread." (PMID 39897330, 2025). "Biomarkers, such as ferritin, leptin, resistin, interleukin-6 (IL-6), insulin, tumor necrosis factor-alpha and plasminogen activator inhibitor-1 (PAI-1), play crucial roles in the pathophysiology of obesity." (PMID 41011232, 2025). "Since obesity induced by chronic activation of non-LepR neurons is leptin resistant, we next explored the possibility that non-LepR neurons function directly downstream of LepR neurons." (PMID 40540394, 2025). "Although leptin has clearly been effective in inducing weight loss and improving insulin sensitivity in leptin-deficient individuals, the same has not been observed in those with leptin excess in lifestyle-related obesity." (PMID 40214973, 2025).
Obesity (continued). "In children with obesity, FFA and adipokines (e.g., leptin) secreted by enlarged adipocytes promote the differentiation of monocytes to proinflammatory macrophages in adipose tissues, leading to the production of inflammatory cytokines including TNF-α and IL-6." (PMID 40302954, 2024). "It further aims to improve the understanding of the role of leptin in non-mammals and is expected to provide theoretical references for solving the obesity and diabetes problems currently faced by human beings." (PMID 39519205, 2024). "Furthermore, studies have shown that obesity-related insulin resistance and compensatory hyperinsulinemia contribute to the HPG axis activation and increased leptin and LH levels." (PMID 38535297, 2024). "Our metabolic screening also showed that U90926 deficiency does not impact other major plasma biomarkers of obesity, such as fibroblast growth factor 21 (FGF21), leptin, and insulin." (PMID 38171546, 2024). "Studies using mild obese asthma mouse models have demonstrated that obesity prompts changes in adipokine secretion, such as leptin, adiponectin, and VEGF, yet there was no direct effect on airway hyperreactivity and lung inflammation development." (PMID 40474934, 2024). "Moreover, a positive correlation between bacteria(Lachnospiraceae_NK4A136-group and Ruminococcus) and obesity-related indicators (MG, AGEs, MDA, orexigenic neuropeptides,jejunum leptin, and liver leptin) was observed in HFD-fed rats." (PMID 38659208, 2024). "In patients without obesity, fasting leptin levels are 2-fold higher in patients with CS compared to nonobese controls (33.5 vs 14.2 ng/mL)." (PMID 38795365, 2024). "A prospective non-randomized study with 17 patients noticed a reduction in lean body mass reaching 2.0 kg (p = 0.005) at 6 months compared to baseline, although the FDA has not yet approved any leptin analogues for the treatment of non-monogenic obesity." (PMID 39125772, 2024). "Exercise training combined with PBD are suggested as non-invasive interventions for reducing leptin and increasing adiponectin levels to control body mass and other disorders related to obesity in adults with or without chronic diseases." (PMID 39444577, 2024). "Such obesity-induced hyperleptinemia contributes to central leptin resistance and such patients do not respond to exogenously administered leptin." (PMID 38707092, 2024). "One recent investigation found decreased leptin levels in individuals with obesity (and also in a subanalysis with females only with obesity) after an oral glucose tolerance test but not after an oral fat tolerance test." (PMID 39771019, 2024). "In addition, obesity and asthma showed a significant interaction effect on the plasma levels of IL-5, IL-10, IL-17A, IL-33, TNF-α, and leptin." (PMID 39902293, 2024). "In individuals with obesity, there is a correlation between high levels of DPP4 and several factors, including increased concentrations of macrophages in WAT, elevated levels of leptin and inflammatory cytokines, and reduced adiponectin concentrations." (PMID 39335642, 2024). "Obesity often correlates with heightened levels of systemic pro-inflammatory markers like C-reactive protein, TNF-α, TGF-β, leptin, and IL-6, and we have shown that reducing TNF-α and TGF-β1 levels improved AHR and fibrosis in the same HFD-induced obesity model." (PMID 38762465, 2024). "Thus, leptin induces hypertension by acting also in the carotid bodies, which opens the perspective for TRPM7 blockers as a potential therapy in obesity-related hypertension." (PMID 38186879, 2024). "Although there have been several studies on the relationship between leptin levels and diabetes or obesity, the conclusions have not been consistent." (PMID 39684379, 2024). "The observed results of leptin have not been characterized in prostate cancer; however, given the high correlation between obesity and prostate cancer, it is assumed that leptin will have similar effects on prostate TME." (PMID 39596205, 2024).
Obesity (continued). "In order to further characterise the role of leptin in the modulation of NLRP3 inflammasome profile changes and subsequent macrophage activation in the ovary during obesity, we started by characterising the expression of NLRP3 components in the ovaries of db/db mice." (PMID 38580672, 2024). "Furthermore, IR, leptin excess, and hypoxia during obstructive sleep apnea (OSA), favored by obesity, activate the sympathetic nervous system, promoting the development of hypertension." (PMID 39599588, 2024). "The mice do not exhibit overweight or obesity characteristics, and there is no IR with low serum insulin, low fasting blood glucose, and low leptin." (PMID 39840105, 2024). "Regarding the onset and progression of fat deposits and the development of obesity in these mice, it has been noted that the NZB/W mice have elevated blood levels of leptin, and that leptin administration to such mice accelerated autoantibody production and renal disease." (PMID 39199293, 2024). "In a previous study of diet-induced obesity in rats (55% energy from fat), the MUFA content of the diet rather than the size of the animals appeared to have the greatest effect on adiponectin levels in adipose tissue, whereas circulating leptin was unchanged." (PMID 38732558, 2024). "The suggested hypothesis of CART-mediated obesity-related infertility proposes that CART acts as a mediator of ovarian metabolic dysfunction, impacting leptin’s capacity to control gonadotropin signaling and estradiol synthesis." (PMID 39595164, 2024). "In contrast, a lack of leptin alters essential brain functions currently under investigation for their potential impact on AD development, particularly obesity." (PMID 38933275, 2024). "DNA methylation is closely related to the development of obesity by affecting gene expression, then disrupting the regulatory balance between obesity-promoting genes (such as FTO and PPARγ) and anti-obesity genes (such as LEP, GLP-1R, and POMC)." (PMID 39200098, 2024). "Our study demonstrated that loss of Tet2 in adipocytes led to the reduction of circulating leptin levels and a marked increase in basal and leptin-induced p-STAT3 levels in the hypothalamus, accompanied by resistance to HFD-induced obesity." (PMID 38561362, 2024). "Leptin also stimulates the SNS and increases BP and could be an important link between obesity and hypertension." (PMID 38186879, 2024). "The inability of leptin to exert its anorexigenic effects in obese individuals and, consequently, the lack of clinical utility in obesity are defined as leptin resistance." (PMID 38397015, 2024). "On the other hand, increased leptin activity, impaired chemoreceptor and baroreceptor reflexes, renal ectopic fat and activated RAAS appear to substantially contribute to SNS overactivation in obesity." (PMID 38186879, 2024). "In states of obesity, the gram-positive bacterial production of lipoteichoic acid (LTA) or its gram-negative equivalent, LPS, induces local inflammation, diminishing NG sensitivity to leptin, but also to CCK, GLP-1, and PYY." (PMID 38613104, 2024). "Individuals with obesity typically have chronically elevated leptin levels, indicating leptin resistance, in which increased leptin signaling does not translate into appropriate appetite suppressant effects." (PMID 39444577, 2024). "The absence of leptin or its receptors results in uncontrolled hunger, potentially leading to obesity." (PMID 38397015, 2024). "Furthermore, we identify the crucial role of adipocyte TET2 in HFD-induced obesity and elucidate that TET2 interacts with transcription factor C/EBPα to control leptin gene expression, thereby regulating body weight." (PMID 38561362, 2024). "We analyzed the levels of these adipokines based on BMI and identified an obesity effect on leptin and IL-6 but not adiponectin and FABP4." (PMID 39408921, 2024). "Contrary to the initial idea of leptin being an “antiobesity hormone,” avoidance of obesity is not leptin’s dominant physiologic role." (PMID 38165042, 2024).